EGFR (epidermal growth factor receptor)
Diseases named in the same sentence as EGFR in open-access papers (continued):
Sharing a sentence is not in itself a finding about the gene and the disease.
small cell lung carcinoma (continued). "As a preliminary feasibility experiment, polymerizing non-small cell lung cancer cells targeted with commercial FITC-labeled EGFR antibodies resulted in polymer formation that stabilized cells in hypotonic lysing conditions." (PMID 29309430, 2018). "For EGFR overexpressing cells, we used non-small cell lung cancer cell line HCC827 which has ∼358,000 receptors per cell." (PMID 30323890, 2018). "This situation is somewhat analogous to the emergence of small cell lung cancer in epidermal growth factor receptor-mutant adenocarcinoma treated with the inhibitor of epidermal growth factor receptor." (PMID 28604629, 2017). "The small cell lung cancer (SCLC) transformation is observed in ~14% of the re-biopsy tumors from patients after resistance to first-generation EGFR-TKIs." (PMID 29163853, 2017). "Transformation to small cell lung cancer (SCLC) is found in some NSCLCs with an acquired resistance to EGFR TKIs." (PMID 29140271, 2017). "SKBR3 is a non-TNBC breast adenocarcinoma cell line that expresses wild-type EGFR and PC9 is non-small cell lung cancer cell line that expresses EGFR with a delta E746-A750 deletion in the tyrosine kinase domain." (PMID 28593948, 2017). "Small cell lung cancer transformation has been reported as a mechanism of acquired resistance to EGFR TKI, and it accounts for 3–14% of cases who had acquired resistance to EGFR TKIs." (PMID 26862733, 2016). "In non-small cell lung cancer cell lines, EGFR turnover rates ranged from 28 hours in A431 cells (WT) to 7.5 hours in the PC-9 cells (Del 746–750 mutant)." (PMID 26689952, 2015). "Tumor cells acquire resistance to these compounds through multiple mechanisms, including a second-site mutation (T790M) in EGFR, amplification of MET or ERBB2, and conversion to a small cell lung cancer phenotype." (PMID 26047463, 2015). "The mechanisms responsible for acquired resistance to EGFR-TKIs include secondary EGFR T790 M mutation, MET amplification, epithelial-to-mesenchymal transition (EMT) signature, histologic transformation to small cell lung cancer, and AXL kinase activation." (PMID 25552401, 2015). "The overexpression of EGFR was detected in 33.33% and 62.71% of small-cell lung carcinoma (SCLC) and non-small-cell lung carcinoma (NSCLC), respectively." (PMID 26317020, 2013). "Small cell lung cancer (SCLC) transformation is an incompletely characterized mechanism of resistance to epidermal growth factor receptor tyrosine kinase inhibitors (EGFR-TKIs) in EGFR-mutant cancers, limiting development of optimal treatment approaches." (PMID 41574603, 2026). "PIK3CA alterations were observed in approximately 20% of EGFR-mutated small-cell lung cancer cases, although no statistically supported association with never-smoker status can be concluded from these data." (PMID 41594221, 2026). "This phenomenon, primarily observed in adenocarcinoma (ADC) with EGFR mutations under tyrosine kinase inhibitor (TKI) treatment, leads to histological transformation into small-cell lung cancer (SCLC), commonly associated with an aggressive clinical course and poor prognosis." (PMID 40507907, 2025). "However, resistance develops through mechanisms such as secondary EGFR mutations, alterations to pathways downstream of or alternative to EGFR, or small cell lung cancer (SCLC) transformation." (PMID 39972134, 2025). "The 2020 Chinese Society of Clinical Oncology (CSCO) Guidelines for the Diagnosis and Treatment of Small Cell Lung Cancer recommend standard SCLC chemotherapy plus continued original EGFR-TKI as the treatment regimen for patients with transformed SCLC (Class III evidence, Class III recommendation)." (PMID 40134592, 2025). "Patients with small-cell lung cancer, no EGFR mutations, organoid growth, or quality control (QC) failures were excluded from the analysis." (PMID 38773241, 2024).
small cell lung carcinoma (continued). "Furthermore, EMT is one of the key resistance mechanisms against EGFR-TKIs including other mechanisms such as the ’gatekeeper’ T790M mutation, histologic transformation from NSCLC to small-cell lung cancer, and concurrent molecular or genetic alterations." (PMID 39766891, 2024). "While previously reported in small-cell lung carcinoma (SCLC), the clinical significance of this specific mutation co-occurring with an EGFR exon 18 mutation in adenocarcinoma remains unknown." (PMID 39497876, 2024). "With respect to HCRU, the number of hospitalizations and ambulatory care encounters among individuals with eNSCLC was comparable to that of individuals with extensive-stage small-cell lung cancer and EGFR-positive metastatic NSCLC reported in prior investigations." (PMID 38248115, 2024). "Activation of autophagy flux induced resistance to EGFR-TKIs in non-small cell lung cancer cells." (PMID 37735252, 2023). "EGFR-TKIs may elicit multiple mechanisms of resistance including T790M gatekeeper EGFR mutation, MET amplification, conversion to small cell lung cancer, and PI3KCA mutation." (PMID 35931945, 2022). "Multivariate analyses revealed that old age, male sex, small cell lung cancer, late-stage cancer, and negative EGFR were independent risk factors for poor prognosis." (PMID 36233811, 2022). "Notably this included small cell lung cancer (SCLC) with Study B-005 (lurbinectedin), EGFR mutated non-small cell lung cancer (NSCLC) with ARCHER 1050 (dacomitinib) and triple negative breast cancer (TNBC) with IMMU-132-01 (sacituzumab govitecan)." (PMID 35047397, 2021). "Similarly, EGFR-driven NSCLC was observed to convert towards a small cell lung cancer (SCLC) phenotype upon EGFR inhibition, thus leading to therapy evasion." (PMID 32595946, 2020). "An innate tumor resistance to epidermal growth factor receptor (EGFR) small molecule inhibitors was found in 10% of non-small cell and lung carcinoma patients and the Cripto expression was higher in the cases exhibiting resistance compared to therapy responders." (PMID 32517087, 2020). "EGFR pathway-independent mechanisms include MET amplification, HER2 amplification, FGFR1 amplification, BRAF mutation, KRAS mutation, and histologic transformation to small cell lung cancer." (PMID 30875928, 2019). "Further, patients with never/ever smoking history who present with small-cell lung cancer have a different mutation profile compared with smokers, including a high frequency of EGFR, MET, and SMAD4 mutations." (PMID 31058075, 2019). "Small-cell lung cancer transformation is rare in NSCLC patients resistant to EGFR-TKIs treatment." (PMID 29713646, 2018). "Clinically, EGFR-positive NSCLC acquires several resistance mechanisms during EGFR-TKI treatment, such as the emergence of a secondary mutation (T790M), MET gene amplification, and transformation to small cell lung cancer." (PMID 30290647, 2018). "Several resistance mechanisms have been found and thoroughly described including the EGFR T790M mutation, MET proto-oncogene (MET) gene amplification, development of epithelial to mesenchymal transition (EMT), and transition to a small cell lung cancer (SCLC) phenotype." (PMID 28978110, 2017). "Other aberrations that may give rise to EGFR TKI resistance include PIK3CA mutations, EMT or MET amplification, or conversion to small cell lung cancer histology." (PMID 22363766, 2012). "The authors categorize resistance into EGFR-dependent mechanisms (e.g., secondary mutations like T790M and C797S), bypass pathway activation (e.g., MET or HER2 amplification, KRAS mutations, and BRAF mutations), and histologic transformation (e.g., small-cell lung cancer)." (PMID 40416863, 2025).
small cell lung carcinoma (continued). "Although EGFR mutations are not typically associated with neuroendocrine small cell lung carcinoma and no HIV integration was detected in the EGFR locus, the presence of a deleterious EGFR mutation may contribute to reduced EGFR expression in tumor regions." (PMID 40710199, 2025). "Osimertinib resistance can be broadly grouped into EGFR-dependent mechanisms, such as C797X mutations, and EGFR-independent mechanisms, such as the amplification of MET and HER2, epithelial-mesenchymal transition (EMT) and small cell lung cancer transformation." (PMID 39227379, 2024). "The mechanisms of acquired resistance to EGFR-TKIs involve the second-site mutations of EGFR (such as T790M gatekeeper mutation), activation of the bypass signaling pathways, epithelial-mesenchymal transition (EMT), the transformation of NSCLC to small cell lung cancer tissue, etc.." (PMID 36744262, 2023). "Besides the classical EGFR-T790M mutation and transformation to a small-cell lung cancer (SCLC) phenotype, aberrant activations of bypass signaling pathways responsible for EGFR TKI resistance have been identified, such as c-MET amplification and abnormal activation of the PI3K/AKT pathway." (PMID 35399731, 2022). "In addition to the drug resistance conferred by the C797S mutation in EGFR, amplification of the MET gene as a bypass pathway, alteration in RAS-RAF-MAPK pathway, ROS1 fusion gene, PIK3CA mutation, and transformation to small cell lung cancer are other mechanisms that impart drug resistance." (PMID 34831415, 2021). "Interestingly, patients that did not have EGFR-T790M mutation induced EGFR-independent mechanisms on acquiring resistance, such as activation of bypass signaling and transformation to small cell lung cancer." (PMID 30875919, 2019). "Finally, complex phenotypic transformations such as epithelial-to-mesenchymal transition or transformation into small-cell-lung cancer (SCLC) might also carry resistance to EGFR TKIs." (PMID 31557965, 2019). "Several mechanisms of secondary resistance have been revealed, including: EGFR T790M mutation (the most frequent), mesenchymal-epithelial transition, MET amplification, phosphatidylinositol-4-5-bisphosphate 3-kinase mutations (PI3K) and small-cell lung cancer transformation." (PMID 27926478, 2016). "Small-cell lung cancer with epidermal growth factor receptor (EGFR) gene mutation typically manifests as a transformation occurring after EGFR tyrosine kinase inhibitor therapy for adenocarcinoma with EGFR mutation, whereas primary small-cell lung cancer showing EGFR mutation is extremely rare." (PMID 24195468, 2013). "Small-cell lung cancer (SCLC) transformation, as one of the major mechanisms of EGFR-TKI resistance, was reported in 3-14%." (PMID 40437627, 2025). "Although most cases of neuroendocrine transformation have been reported in EGFR-mutant LUAD, the transformation of lung squamous cell carcinoma (LUSC) to small-cell lung cancer (SCLC) is a recognized but relatively rare phenomenon." (PMID 40507907, 2025). "Upon demonstrating resistance to EGFR-TKI therapy, a needle biopsy of the primary site subsequently identified the presence of small cell lung cancer." (PMID 39995840, 2025). "Less common mechanisms of acquired resistance for the first-/second-generation EGFR-TKI include MET amplification, ERBB2 amplification, transformation to small-cell lung cancer, and others." (PMID 40028158, 2025). "The PG acquired resistance to EGFR-TKIs through the MET amplification (27, 50%) and small cell lung cancer transformation (16, 30%) and 18% of them reported multiple resistance mechanisms." (PMID 38402169, 2024). "The transformation from adenocarcinoma to small cell lung cancer (SCLC) and squamous cell carcinoma (SCC) has been described after treatment with third-generation EGFR-TKIs like osimertinib as first-line or second-line." (PMID 38966183, 2024).
small cell lung carcinoma (continued). "A complex and poorly understood mechanism of EGFR inhibitor resistance involves transformation into new histologic subtypes, including epithelial-to-mesenchymal transition (EMT) and small cell lung cancer (SCLC) transformation of NSCLC cells." (PMID 36902723, 2023). "Small-cell lung cancer (SCLC) transformation has been described as another resistance mechanism, accounting for 3 to 10% of all the EGFR-TKI-resistant cases." (PMID 35264788, 2022). "Histologic transformation from NSCLC to small cell lung cancer (SCLC) is a known mechanism of resistance to first- and second-generation EGFR-TKIs (14%) and was first described in 2011." (PMID 34638411, 2021). "Other known biological resistance mechanisms include MET amplification, EGFR amplification, PIK3CA amplification, HER2 amplification, and histologic transformation to small cell lung cancer." (PMID 30875928, 2019). "Specifically, conversion to small cell lung cancer histology and epithelial-mesenchymal transition (EMT) have been observed in EGFR mutant patients and cell lines resistant to EGFR inhibitors." (PMID 24349229, 2013). "We next examined the effect of knocking down Odin protein expression in the non-small cell lung carcinoma cell line RVH6849, which expresses wild type EGFR, but at a level more than 10-fold higher than HEK293 as measured by SRM-MS." (PMID 23825523, 2013). "EGFR, p-AKT, p-ERK, p-mTOR and p-p70s6K protein expressions were studied by immunohistochemistry in 107 small cell lung carcinomas and correlated with clinicopathological parameters." (PMID 20683448, 2010). "Small cell lung cancer (SCLC) transformation has been reported in 3–14% of patients treated with first- and second-generation EGFR TKI, and in 5–20% of those receiving Osimertinib and has also been observed in ALK- and ROS1-rearranged tumors, suggesting that it is independent of TKI class." (PMID 41228269, 2025). "For example, transformed small cell lung cancer (SCLC) diverges from its non-transformed EGFR-mutant adenocarcinoma precursors by lacking EGFR expression, thereby rendering them resistant to EGFR inhibitors." (PMID 38329598, 2024). "HIF-1, NF-κB, IL-17, EGFR, MAPK, endocrine resistance, tyrosine kinase resistance, platinum drug resistance, antifolate resistance, arginine biosynthesis, sphingolipid, human cytomegalovirus infection, Kaposi’s sarcoma, small cell lung cancer etc." (PMID 36685935, 2022). "In addition to EGFR dependent resistance mechanisms, the activation of bypass pathways through the MET, AXL, IGF1R axis or the phenotypic transformation to small-cell lung cancer (SCLC) has been reported to drive resistant responses to 1G and 2G TKIs17–20." (PMID 34385540, 2021). "Using ELISAs, we determined that the EGFR wild type cell line H838 and small cell lung cancer cell line H1339 expressed EPO-R, while the EGFR gene mutation cells lines (H1975, HCC827, and H1650) did not have expression detectable above the control." (PMID 32922549, 2020). "In vitro studies using breast and small cell lung cancer cell lines, have shown that INCB3619 reduced the cleavage of HER2 and amphiregulin, thereby sensitising cells to the EGFR tyrosine kinase inhibitor, gefintinib or a dual EGFR/HER2 inhibitor, GW2974." (PMID 30188954, 2018). "In the off-target group, bypass signaling activation (such as the other RTKs: EGFR, KIT, IGF1R and downstream signaling molecules; SRC, MEK/ERK) and morphological alterations (small cell lung cancer and epithelial-mesenchymal transition) contribute to this resistance." (PMID 30404198, 2018). "In addition, studies suggested that cells transformed from NSCLC to small cell lung cancer (SCLC) will be sensitivity to navitoclax, and down-regulation of EGFR and RB were biomarkers for this transform." (PMID 27835594, 2016).
small cell lung carcinoma (continued). "Beyond first-line treatment, in particular for patients with wild type EGFR who have received first-line chemotherapy, recommendations regarding the potential benefits of TKIs are less clear (NICE TA162, NCCN Guidelines for Non–Small-Cell Lung Cancer)." (PMID 25547901, 2015). "Further, genes in the EGFR/ITGB1-T4R differential network are connected with various cancers, including prostate, and small cell lung cancer, suggesting that despite phenotypic reversion to normal, some malignant genes remain active in the EGFR/ITGB1-T4R cells." (PMID 25057922, 2014). "Small cell lung cancer exhibited increased expression of MRP5, activation of Wnt pathway inhibitors, and upregulation of p38 MAPK activating genes, while NSCLC showed downregulation of CDKN2A, and upregulation of MAPK9 and EGFR." (PMID 16705311, 2006). "In 11 small-cell lung cancer (SCLC) cell lines, EGFR mRNA was detected by Northern blot analysis." (PMID 9744504, 1998). "Moreover, the prevalence of EGFR is highest among patients with NSCLC with an adenocarcinoma histology, while it occurs only rarely in NSCLC patients with squamous cell carcinoma histology and small cell lung cancer (SCLC)." (PMID 34202748, 2021). "In lung cancer, classifiers for NSCLC and small cell lung carcinoma (SCLC) reached an accuracy of 92%, but they were unable to predict molecular markers such as EGFR without dedicated retraining." (PMID 41316486, 2025). "Thus, the series of second- and third-line EGFR or ALK TKIs is eventually rendered inactive by activation of alternative kinases and, in the case of NSCLC, by a histological switch to a small cell lung cancer (SCLC) phenotype, which is not susceptible to the original TKIs." (PMID 35582610, 2020). "Second, the agrin–EGFR co‐expression observed in various pathologic grades of LUAD pertained to solid, papillary, and acinar adenocarcinomas but was not obvious in small cell lung cancers from an Asian cohort." (PMID 40165020, 2025).